BRCA1 (BRCA1 DNA repair associated)
Diseases named in the same sentence as BRCA1 in open-access papers (continued):
Sharing a sentence is not in itself a finding about the gene and the disease.
diabetes (25 papers, 2013 to 2025). "For instance, studies indicate that insulin resistance, a crucial aspect of diabetes, is caused by a BRCA1 deficit." (PMID 40138287, 2025). "BRCA1/2 mutations raise type 2 diabetes mellitus risk, with high BMI being one potential factor via metabolic misregulation." (PMID 40989682, 2025). "The public health implications of screening for BRCA1 mutations and diabetes mellitus type 2 should also be further researched." (PMID 37109551, 2023). "In conclusion, the association between metabolic disorders, including diabetes and the metabolic syndrome, and BRCA1 and BRCA2 mutations is of major clinical relevance and warrants further investigation." (PMID 35432218, 2022). "The correlation between metabolic disorders, including diabetes and the metabolic syndrome, and BRCA1 mutations, are discussed in this article." (PMID 35432218, 2022). "Intriguingly, women with BRCA1 mutations are more prone to developing diabetes, a risk that also increases in women with a high BMI." (PMID 31940810, 2020). "This suggested that BRCA1 may be an effective target for treating diseases such as diabetes and metabolic dysfunction-associated steatotic liver disease." (PMID 40138287, 2025). "Moreover, CYP1A2 activity has also been linked to type 2 diabetes mellitus and has demonstrated interaction effects with coffee consumption and BRCA1 mutation." (PMID 36581893, 2022). "A downregulation of this pathway activity is consistent with partial BRCA1/2 inhibition in the presence of diabetes and hyperglycemia." (PMID 37906280, 2023). "We identified 160 variants in BRCA1 and 274 variants in BRCA2 based on the analysis of 3842 Mexican population samples from the SIGMA Diabetes database." (PMID 30630528, 2019). "This suggests that BRCA1 may be involved in regulating lipid metabolism in conditions similar to diabetes." (PMID 40138287, 2025). "However, diabetes may induce “BRCAness” by an alternative mechanism involving loss of gene expression, since BRCA1 and BRCA2 transcripts were commonly downregulated in the clinical samples and xenografts in the presence of diabetes." (PMID 37906280, 2023). "There is growing evidence of successful and rapid dissemination of genetic information into routine clinical care in nurse-led services such as diabetes services in the United Kingdom and a Mainstreaming Cancer Genetics (MCG) service for BRCA1/2 at the Nottingham University Hospitals NHS Trust." (PMID 37396047, 2023).
uterine cancer (25 papers, 2008 to 2025). Primary or metastatic malignant neoplasm involving the uterine corpus and/or the cervix. "In this study, we aim to investigate the association between BRCA1/2 mutation and uterine cancer incidence." (PMID 38297203, 2024). "From the three cases diagnosed with uterus cancer, only one case revealed positivity, where a pathogenic variant was found in the BRCA1 gene." (PMID 39148954, 2024). "Uterine cancer risk in BRCA1/2m women and its significance in the BRCA mutated condition are still beyond controversy." (PMID 38297203, 2024). "Compared to the general population, women with a deleterious BRCA1 or BRCA2 mutation had a roughly 2.5-fold greater risk of getting uterine cancer, according to the cohort study on the rate of BRCA mutation in uterine cancer." (PMID 38297203, 2024). "We systematically searched three databases including PubMed, Scopus, and Google Scholar up to August 2023; and reviewed 23 cohorts and cross-sectional studies to explore the association between BRCA1/2 mutations and uterine cancer incidence." (PMID 38297203, 2024). "The prevalence of BRCA mutation varied from 0% to 27.2% in patients with uterine cancer, and the currency of uterine cancer ranged from 0.53% to 1.87% in BRCA1/2 mutation carriers according to the baseline table." (PMID 38297203, 2024). "Redox failure in women with BRCA1/2 insufficiency increases the risk for breast/ovarian/uterine cancers." (PMID 39201170, 2024). "Our meta-analysis investigates 2% prevalence of BRCA1/2 mutation in patients with uterine cancer." (PMID 38297203, 2024). "Our meta-analysis investigates a 2% prevalence of BRCA1/2 mutation in patients with uterine cancer." (PMID 38297203, 2024). "BRCA1 somatic variants were more prevalent than germline variants in uterine cancers." (PMID 37916805, 2023). "The uterine cancer of III:1 could therefore be misinterpreted as caused by the BRCA1 germline mutation." (PMID 23164213, 2012). "In our sample uterine cancer was related to the BRCA1 gene mutation." (PMID 18783588, 2008). "However, not only tamoxifen but also germline BRCA1 5382insC may increase the risk of this histopathological subtype of uterine cancer." (PMID 37047678, 2023). "One of the studies just reported the prevalence of BRCA1 in uterine cancer cases and one of them didn’t segregate the BRCA1 and BRCA2 prevalence." (PMID 38297203, 2024). "According to meta-analysis the prevalence of the BRCA1/2 gene in patients with uterine cancer was 0.02 (95%CI = [0.01,0.03], I2 = 94.82%, p < 0.01)." (PMID 38297203, 2024). "The aim of this systematic review and meta-analysis is to determine how BRCA1/2 affects uterine cancer and provide answers to these concerns." (PMID 38297203, 2024). "Known pathogenic variation in SDHB/RET, BRCA1/2, and MMR genes is thought to be responsible for a subset of pheochromocytoma and paraganglioma, breast, ovarian, colon, and uterine cancers in TCGA." (PMID 30217226, 2018). "BRCA1 or BRCA2 mutation can marginally increase cervical and uterine cancer incidence." (PMID 34577828, 2021). "Second, the reason that the results for uterine cancer were lower than those of other cancers is that BRCA1 and BRCA2 mutant genes are related to both breast and uterine cancer." (PMID 36142316, 2022).
Alzheimer disease (23 papers, 2007 to 2025). A progressive, neurodegenerative disease characterized by loss of function and death of nerve cells in several areas of the brain leading to loss of cognitive function such as memory and language. "In contrast, under pathological conditions, Brca1 is abnormally colocalized with Tau in neurofibrillary tangles, a hallmark lesion of Alzheimer’s disease." (PMID 36430332, 2022). "This analysis was capable of identifying risk factors with strong effects, such as the association of the ε4 allele of the APOE gene with Alzheimer’s disease (AD) and genetic risk factors for breast cancer in the BRCA1 and BRCA2 genes." (PMID 34831407, 2021). "Although BRCA1 expression can stimulate apoptosis by initiating cell cycle re-entry in neurons associated with Alzheimer’s disease, BRCA1 can also promote cell cycle arrest and inhibit cell cycle progression into S-phase in human cancer cells." (PMID 34222870, 2021). "Studies on preferences for preventive and risk-reducing treatments have been conducted, for example, in individuals at risk of rheumatoid arthritis, women with the BRCA1/2 gene, and individuals at risk of Alzheimer's disease." (PMID 31971833, 2020). "Amyloid-beta, a peptide associated with Alzheimer's disease, downregulates BRCA1 leading to the formation of DNA DSBs." (PMID 28904242, 2017). "Brca1 has been implicated in preventing apoptosis in early neuronal progenitors and its expression in adult life is associated with Alzheimer's disease." (PMID 20509949, 2010). "Indeed, BRCA1 loss in a mice model of Alzheimer’s disease resulted in increased neuronal double-stranded breaks without an increase in neuronal apoptosis." (PMID 34222870, 2021). "Furthermore, BRCA1 overactivation has been associated with driving neuronal death associated with Alzheimer’s disease by promoting cell cycle re-entry." (PMID 34222870, 2021). "In several neurodegenerative diseases, including Alzheimer’s disease and other tauopathies, BRCA1 dysregulation and mislocalization have also been reported." (PMID 37638313, 2023). "Further experiments investigating mice with a BRCA1 knockdown in the brain showed an increase in neuronal double-stranded breaks and impairments in memory and learning, which were exacerbated in Alzheimer’s disease mice." (PMID 34222870, 2021). "In patients with Alzheimer’s disease and mild cognitive impairment, BRCA1 appeared to be depleted in hippocampal regions compared to control patients, and was instead enriched at histopathological legions." (PMID 34222870, 2021). "A recent study also demonstrates a significant increase of the BRCA1 gene expression in the brain of Alzheimer’s disease (AD) patients, suggesting an important role of BRCA1 in combating oxidative DNA damage that occurs in AD patients’ brains." (PMID 31963223, 2020). "In Alzheimer’s disease (AD), we previously reported mislocalization of the DNA repair nuclear protein BRCA1, its coaggregation with tau, and the possible importance of the subsequent DNA repair dysfunction." (PMID 31861888, 2019). "Some studies suggested that the function of Brca1 was unique in neurons and increasing Brca1 could promote cell cycle re-entry and induce neuronal death in Alzheimer’s diseases." (PMID 36430332, 2022). "Moreover, levels of BRCA1 in hippocampal neurons were reduced in post-mortem brains of Alzheimer’s disease and mild cognitive impairment patients compared to control patients with no cognitive deficits." (PMID 34222870, 2021). "In addition to well-studied BRCA1 dysregulation in cancer cells, BRCA1 protein is downregulated in the brains of patients with Alzheimer's disease." (PMID 28904242, 2017).
Alzheimer disease (continued). "Mislocalization of BRCA1 to the cytoplasm, previously identified in several models of tau-dependent neurodegeneration, was also found to be higher in subjects with both clinical and pathological Alzheimer’s disease compared to those with only disease pathology and controls." (PMID 34222870, 2021). "They include disclaimers for consumers to acknowledge prior to release of results, recommend genetic counselling and consumers can exclude specific results, including BRCA1 and BRCA2 and Alzheimer’s Disease." (PMID 39880983, 2025). "Using brain tissue from pure LBD, LBD with Alzheimer disease (AD) co-pathology (LBD-AD), and control cases, the immunohistochemical distributions of BRCA1, pBRCA1, its binding partner BARD1, and 53BP1 were examined." (PMID 39907307, 2025).
ductal carcinoma (23 papers, 2004 to 2025). "The SUM149PT cell line was originally derived from a breast ductal carcinoma and contained a homozygous BRCA1 pathogenic variant, c.2169delT, which resulted in a frameshift that led to a premature stop codon (p.P724Lfs*12)." (PMID 40982437, 2025). "In line with the existing evidence, tumors from BRCA1/2 carriers were more frequently ductal carcinomas, whereas non-BRCA1/2 carriers variants were more likely to have lobular BC." (PMID 37791908, 2023). "BRCA1 (n = 5) and BRCA2 (n = 5) were the most frequently mutated genes, as commonly reported in ductal breast carcinoma." (PMID 38308423, 2024). "For this, we cultured primary CAFs from Infiltrating Ductal Carcinoma (IDC) (n = 4) with cmHCC1937 or cmHCC1937/wt BRCA1 for 5 days." (PMID 30224826, 2018). "BRCA1 tumors are frequently high-grade (grade 3), ductal carcinomas with necrotic areas and lymphocytic infiltration." (PMID 23704984, 2013). "Similarly, ductal carcinomas were more frequent in BRCA1 carriers (p < 0.05), while tumors of mixed histology were significantly associated with BRCA2-positive tumors (p < 0.05)." (PMID 39001430, 2024). "The histological subtypes were not significantly different between groups (p = 0.495), with most of the patients having a ductal carcinoma (59.3%—BRCA-negative group; 50%—BRCA1 group; 63.6%—BRCA2 group)." (PMID 41002733, 2025).
neuroblastoma (23 papers, 2012 to 2025). Neuroblastoma (NB) is the most common solid, extracranial childhood tumor. "The BRCA1–Neuroblastoma risk ratio is still under study; therefore, the implications of this variant in tumor development are currently undetermined." (PMID 34771502, 2021). "The relationship between BRCA1 mutations and predisposition to neuroblastoma is based on casual findings in specific cases, such as our patient." (PMID 34771502, 2021). "Thus, alterations other than BRCA1/2 mutations may cause the apparent HRR deficiency in neuroblastomas." (PMID 37868040, 2023). "BRCA1 PGVs were identified in the germline of children diagnosed with what appeared to be non-syndromic neuroblastoma, and also in treatment related secondary malignancies." (PMID 34680915, 2021). "On the other hand, a subset of high‐risk neuroblastomas harbor increased expression of BARD1, a protein that complexes with BRCA1 to maintain genomic stability but also has oncogenic properties." (PMID 33480449, 2021). "In the present study, we also observed that BRCA1 was degraded by mitochondrial damage in neuroblastoma-derived SH-SY5Y cells." (PMID 33888730, 2021). "We will then focus on evaluating the common BARD1 related SNPs as well as genetic and epigenetic changes that occur in the non-BRCA1-dominant cancers, including neuroblastoma, lung, and gastrointestinal cancers." (PMID 32708251, 2020). "Similar results are obtained from human neuroblastoma cells, suggesting BRCA1 has the potential to affect cell fate determinant in many tumor types." (PMID 31273285, 2019). "Although BRCA1/2 mutations are not frequent in neuroblastoma, we identified mutational signatures related to HRR deficiency in high-risk non-MYCN-amplified patients." (PMID 37868040, 2023). "WEE1, CHEK1, BRCA1, FANCD2, PARP1, and phosphorylation of CHEK1 and ATR were significantly reduced in TRPM2 deleted neuroblastoma and myeloid leukemia cells after doxorubicin treatment." (PMID 35428820, 2022). "The relationship between BRCA1, transcription regulation, and R-loops has been studied in more detail in MYCN-amplified human neuroblastoma cells." (PMID 33755171, 2021). "In the present study, we show that FL BARD1 expression correlates with the expression of genes involved in DNA repair and cell cycle in neuroblastoma samples, probably due to BARD1/BRCA1 heterodimer function." (PMID 32047556, 2020). "Here we show that FL BARD1, as part of the heterodimer BRCA1/BARD1, prevent unscheduled mitotic entry of DNA damaged neuroblastoma cells via a mechanism requiring downregulation of cyclin B/Cdk1 and cell cycle arrest at the G2-M boundary." (PMID 32047556, 2020). "Misregulation of transcription, therefore, might attenuate BRCA1’s role in HR, although MYCN-amplified neuroblastoma cells do not show an increase of unrepaired DSBs." (PMID 33755171, 2021).
medullary carcinoma (22 papers, 2005 to 2024). "Six of the seven carriers showed ductal histology, while one BRCA1 mutation carrier had a medullary carcinoma." (PMID 23110154, 2012). "In BRCA1-related BC, the incidence of typical medullary carcinoma was 19% (6/32) in a French study, 8% (4/49) in a Dutch study, but 0% in a Swedish series of 40 BRCA1-associated tumors." (PMID 16168118, 2005). "Interestingly, the expression of C11orf68 was higher in invasive ductal and lobular carcinomas compared to medullary carcinoma (n = 9) (p < 0.05), which is known to be the only carcinoma associated with BRCA1 mutation." (PMID 26427334, 2015). "A high incidence of medullary carcinoma has been reported among women with BRCA1-associated BC." (PMID 16168118, 2005). "Interestingly, medullary carcinomas presented a significantly higher frequency in carriers compared to non-carriers (11.3% vs. 2.1%; p < 0.05) and were also significantly associated with the presence of BRCA1 PVs (p < 0.05)." (PMID 39001430, 2024). "BRCA1 hypermethylation was reported to be more frequent in medullary carcinomas which are ER−ve and often occur in BRCA1 carriers, but is also observed in mucinous carcinomas which are ER+ve." (PMID 23341493, 2013). "Moreover, Micropapillary carcinoma, mucinous carcinoma as well as medullary carcinoma was found in these patients with BRCA1 LGRs." (PMID 31174498, 2019). "Interestingly, there is lack of data on sporadic medullary carcinomas and its association with BRCA1 germline or somatic mutations." (PMID 29453630, 2018). "The medullary carcinoma accounted for 9.1 % in BRCA1/2 carriers and only 3.4 % in non-carriers (not significant)." (PMID 27129401, 2016). "Medullary carcinomas were seen more in BRCA1 carriers than non-carriers." (PMID 25705321, 2015). "Indication of cases with medullary carcinoma for BRCA1 testing, regardless of the family history, may be helpful in mutation screening." (PMID 16168118, 2005).